IGKV2D-24 (immunoglobulin kappa variable 2D-24 (non-functional))
Description:
Probable non-functional open reading frame (ORF) of V region of the variable domain of immunoglobulin light chains. Non-functional ORF generally cannot participate in the synthesis of a productive immunoglobulin chain due to altered V- (D)-J or switch recombination and/or splicing site (at mRNA level) and/or conserved amino acid change (protein level). Immunoglobulins, also known as antibodies, are membrane-bound or secreted glycoproteins produced by B lymphocytes. In the recognition phase of humoral immunity, the membrane-bound immunoglobulins serve as receptors which, upon binding of a specific antigen, trigger the clonal expansion and differentiation of B lymphocytes into immunoglobulins-secreting plasma cells. Secreted immunoglobulins mediate the effector phase of humoral immunity, which results in the elimination of bound antigens. The antigen binding site is formed by the variable domain of one heavy chain, together with that of its associated light chain. Thus, each immunoglobulin has two antigen binding sites with remarkable affinity for a particular antigen. The variable domains are assembled by a process called V-(D)-J rearrangement and can then be subjected to somatic hypermutations which, after exposure to antigen and selection, allow affinity maturation for a particular antigen.
Synonyms: A7; IGKV2D24
Gene: Immunoglobulin variable (V) gene on chromosome 2 (90,004,797 to 90,005,629, forward strand). Ensembl gene ENSG00000241566.
Subcellular location: Secreted; Cell membrane
Gene Ontology:
Biological process: immune response
Cellular component: extracellular region; immunoglobulin complex; plasma membrane
Homologues: Paralogues in human: IGKV2-24 (98% identical), IGKV2-30 (87% identical), IGKV2D-30 (86% identical), IGKV2D-29 (82% identical), IGKV2D-40 (81% identical), IGKV2-28 (80% identical), IGKV2D-28 (80% identical), IGKV2D-26 (75% identical), IGKV2-40 (68% identical), IGKV4-1 (56% identical), IGKV3-20 (55% identical), IGKV3-11 (54% identical), and 81 more.
Diseases named in the same sentence as IGKV2D-24 in open-access papers:
IGKV2D-24 is named in the same sentence as 3 diseases in open-access papers, as found by Europe PMC text mining. Sharing a sentence is not in itself a finding about the gene and the disease.
IGKV2D-24 shares sentences with these, for which no sentence is quoted: atherosclerosis (1 paper); cancer (1); lung carcinoma (1).